GLS (glutaminase)
Description:
Catalyzes the first reaction in the primary pathway for the renal catabolism of glutamine. Plays a role in maintaining acid-base homeostasis. Regulates the levels of the neurotransmitter glutamate, the main excitatory neurotransmitter in the brain. [Isoform 2]: Lacks catalytic activity.
Synonyms: GLS1; KIAA0838; GAC; GAM; KGA; AAD20; CASGID; DEE71; EIEE71; GDPAG
Tractability: Small molecule: a drug acting on it is in phase 2 or 3 trials; a structure with a bound ligand is known; a high-quality ligand is known. PROTAC: ubiquitination databases record sites on it; its protein half-life has been measured; a small molecule that binds it is known.
Target class: Enzyme; Hydrolase
Chemical probes: A-446 (high quality)
Gene: Protein-coding gene on chromosome 2 (190,880,821 to 190,965,552, forward strand). Ensembl gene ENSG00000115419.
Subcellular location: Mitochondrion (Isoform 1); Cytoplasm, cytosol; Mitochondrion (Isoform 3); Mitochondrion matrix (Glutaminase kidney isoform, mitochondrial 68 kDa chain); Mitochondrion matrix (Glutaminase kidney isoform, mitochondrial 65 kDa chain)
Subcellular location (Human Protein Atlas): Mitochondria
Pathways (Reactome):
Metabolism: Glutamate and glutamine metabolism
Neuronal System: Glutamate Neurotransmitter Release Cycle
Gene Ontology:
Molecular function: glutaminase activity; protein binding
Biological process: intracellular glutamate homeostasis; L-glutamate biosynthetic process; L-glutamine catabolic process; negative regulation of L-glutamine biosynthetic process; protein homotetramerization; amino acid metabolic process; glutamine metabolic process
Cellular component: mitochondrion; mitochondrial matrix; cytosol
Genetic constraint (gnomAD): Loss-of-function variants: 5 observed, 8.5 expected, observed/expected ratio (o/e) 0.59, 90% interval 0.31 to 1.23. That is too few expected variants to judge how well the gene tolerates losing a copy. Missense variants: 245 observed, 210.37 expected, observed/expected ratio (o/e) 1.16, 90% interval 1.05 to 1.29. Synonymous variants: 135 observed, 95.27 expected, observed/expected ratio (o/e) 1.42, 90% interval 1.23 to 1.63.
Gene-disease validity (ClinGen):
ClinGen rates the evidence that GLS causes each of these diseases.
glutaminase deficiency (autosomal recessive): Definitive. Glutaminase deficiency is characterized by refractory seizures, respiratory failure, brain abnormalities and death in the neonatal period, though milder cases with spastic ataxia-dysarthria have also been reported.
infantile cataract, skin abnormalities, glutamate excess, and impaired intellectual development (autosomal dominant): Limited.
Homologues: Orthologues: chimpanzee GLS (100% identical), macaque GLS (99% identical), rabbit GLS (98% identical), pig GLS (97% identical), mouse Gls (95% identical), rat Gls (95% identical), dog GLS (95% identical), guinea pig GLS (88% identical), tropical clawed frog gls (79% identical), zebrafish glsa (70% identical), zebrafish glsb (59% identical), Drosophila melanogaster GLS (45% identical), and 3 more. Paralogues in human: GLS2 (61% identical).
Diseases named in the same sentence as GLS in open-access papers:
GLS is named in the same sentence as 256 diseases in open-access papers, as found by Europe PMC text mining. Sharing a sentence is not in itself a finding about the gene and the disease. The quoted sentences say what the papers report.
breast carcinoma (142 papers, 2010 to 2026). "Previous studies have also implicated GLS as a downstream factor of the proto-oncogene transcription factor c-Jun in the development of breast cancer, as well as in the proliferation of hypoxic gastric cancer cells." (PMID 37665670, 2023). "Further studies have indicated that poor prognosis and glutamine dependency in breast cancer are associated with aberrant GLS expression." (PMID 34638293, 2021). "GLS1 is the most commonly expressed glutaminase isoform in breast cancer cells; however, GLS2 has also been recently linked to sustained cell proliferation and tumorigenesis, including EMT and metastasis." (PMID 34638293, 2021). "Previous studies have found that high expression of GLS is associated with high grade and high metastatic potential in breast cancer." (PMID 33207079, 2021). "The overall aim of this study was to identify metabolic characteristics associated with response to glutaminase inhibitors in breast cancer." (PMID 31088535, 2019). "So, L-ASNase variants with glutaminase co-activity may be the most effective for breast cancer patients as they would both suppress growth of Gln-dependent primary tumors as well as Asn-dependent metastasis." (PMID 35205650, 2022). "2HG overproduction significantly associates with c-Myc activation and poor prognosis in breast carcinomas bearing a stem cell-like transcriptional signature and overexpressing glutaminase, which suggests a functional relationship between glutamine and 2HG metabolism in breast cancer." (PMID 25980580, 2015). "We highlighted that GLS expression might be applicable as a diagnostic biomarker in breast cancer and possess significant implications in the growth and metastasis of tumor and the immune tumor microenvironment, sharing new insights into ontological and personalized medicine." (PMID 37664031, 2023). "This study demonstrates that glutaminase is necessary for luminal breast cancer growth and survival." (PMID 41898641, 2026). "We thus tested the effects of CB839, a GLS inhibitor that is already in early clinical trials in kidney and breast cancer, on the SW48 isogenic panel." (PMID 41266617, 2026). "The current study aimed to determine the importance of glutaminase in Oestrogen Receptor positive/luminal breast cancer to potentially identify therapeutic targets to treat this subtype." (PMID 41898641, 2026). "In vitro studies using luminal breast cancer cells were performed to investigate the effects of siRNA knockdown of glutaminase genes (GLS and GLS2) and inhibition using CB-839 on functional assays." (PMID 41898641, 2026). "HUR has been identified as a regulator of GLS mRNA alternative splicing and isoform translation/stability in breast cancer." (PMID 40598593, 2025). "Enzymes, such as glutaminase and serine hydroxymethyltransferase, often upregulated in breast cancer, represent promising therapeutic targets." (PMID 39973065, 2025). "Glutaminase is highly expressed in breast cancer and is crucial for tumor growth, with therapeutic efforts targeting glutamine catabolism primarily focusing on GLS." (PMID 39973065, 2025). "Recent findings have demonstrated that glutamine-addicted breast cancer cells exhibit a capacity to adapt to chronic glutamine starvation or GLS inhibition through AMPK-mediated upregulation of the serine synthesis pathway." (PMID 40598593, 2025). "Herein we also provide insights supporting the role of selective glutaminase inhibitors as anticancer therapy intercepting oncogenic networks initiated by aberrant expression of circular RNAs such as circPVT1 in breast cancer." (PMID 40114244, 2025). "A positive correlation between c-MYC and GLS expression was evidenced in both breast cancer TGCA database and in MCF-10 A cell clones overexpressing circPVT1." (PMID 40114244, 2025). "Analyzing pathways involving amino acid transporters (e.g., SLC1A5) or enzymes (e.g., GLS) can guide the use of glutaminase inhibitors, such as CB-839, for glutamine-addicted breast cancer." (PMID 39973065, 2025).
breast carcinoma (continued). "In HER2-positive breast cancer models, inhibition of glutaminase (GLS) using the compound CB-839 (telaglenastat) enhanced the efficacy of trastuzumab." (PMID 40051496, 2025). "18F-FGln PET can be used to track the size of the glutamine pool in breast cancer cells with different GLS activity levels, serving as a reverse indicator of glutamine catabolism." (PMID 39973065, 2025). "Polletta and colleagues found that another SIRT5 inhibitor, MC3482, through modifying ε-N-glutamyl lysine, inhibited succinylation of GLS, thereby promoting autophagy in breast cancer cells and inhibiting tumor initiation and progression." (PMID 39781339, 2025). "For example, SIRT5 regulates glutamine metabolism by desuccinylating glutaminase (GLS), which has been demonstrated to promote breast cancer development." (PMID 39781339, 2025). "Etomoxir has enhanced effects when used in combination with a glutaminase inhibitor, as glutamine serves as an important source for tricarboxylic acid cycle substrates, vital for energy supply in breast cancer cells." (PMID 40002245, 2025). "In conclusion, we showed that HuR is a crucial regulator of glutaminase RNA metabolism in breast cancer that affects different aspects of mRNA metabolism, such as mRNA stability and splicing." (PMID 38965208, 2024). "For example, SIRT5-mediated GLS desuccinylation promoted the invasion of breast cancer cell by hampering the ubiquitination-dependent GLS degradation, while the deacetylation of GLS was also reported to contribute to the progression of various carcinomas." (PMID 38315203, 2024). "Altogether, these data reveal the particular importance of HuR in controlling several aspects of GLS mRNA metabolism and protein isoform levels in breast cancer." (PMID 38965208, 2024). "With the discovery of the tumorigenic role of GLS, GLS-driven metabolism pathway alteration was considered contributing to breast cancer progression and pancreatic cancer proliferation." (PMID 38566121, 2024). "HuR also binds to the GLS pre-mRNA intron 14 in prostate and breast cancer cell lines (respectively)." (PMID 38965208, 2024). "Here, the authors show that HuR regulates glutaminase mRNA metabolism in the context of breast cancer." (PMID 38965208, 2024). "ELAVL1 silencing in breast cancer cells affected glutamine metabolism, leading to an increase in glutamine uptake, glutaminase activity, and glutamine dependence for growth." (PMID 38965208, 2024). "In this manuscript, we investigated the relevance of HuR in controlling glutamine metabolism in breast cancer by regulating GLS mRNA metabolism." (PMID 38965208, 2024). "Glutaminase, an enzyme that converts Gln to Glu, is overexpressed in breast cancer, especially in TNBC tumors compared to HER2 and luminal subtypes." (PMID 38921007, 2024). "Here we show that HuR regulates GLS mRNA alternative splicing and isoform translation/stability in breast cancer." (PMID 38965208, 2024). "The GLS enzyme is usually upregulated in various cancer and promotes cancer cell proliferation and suppresses apoptosis, including breast cancer, lung cancer, colon cancer, and so on." (PMID 37582794, 2023). "GAC is often overexpressed in human breast cancer, and it has been demonstrated via immunohistochemistry and protein expression that GLS follows the same pattern in CMTs, as it is highly expressed in high-grade tumors." (PMID 37685021, 2023). "Yuan L found that compound 968 inhibited glutamine metabolism by suppressing the activity of GLS and thus greatly inhibited the proliferation of three breast cancer cell lines." (PMID 37249801, 2023). "In vivo studies confirmed that glutaminase expression was increased in primary TNBC samples compared to other breast cancer subtypes and normal tumor tissue and showed sensitivity to glutaminase inhibitors." (PMID 37731509, 2023). "In the present study, we comprehensively investigated the core gene of this mechanism, GLS, in breast cancer." (PMID 37664031, 2023).
breast carcinoma (continued). "The C-terminal splice variant of GLS, glutaminase C (GAC), is often highly expressed in breast cancer cells and helps satisfy their glutamine addiction." (PMID 35963851, 2022). "Western blot analysis of 17 breast cancer cell lines showed higher protein expression of GLS and TYMS in TNBC cell lines compared to ER+ and HER2-amplified cell lines, and higher expression ALDH18A and PYCR2 in TNBC compared with ER+ cell lines." (PMID 36388465, 2022). "The elevated levels of GAC mRNA (Glutaminase C, a splice variant of Kidney type of GLS1 (KGA)) was also observed in gliomas, colorectal cancers and adenomas, and breast cancer cells." (PMID 35205136, 2022). "RNA-seq analysis of 15 breast cancer cell lines indicated that there was a trend to higher expression of GLS in TNBC cell lines compared with ER+ and HER2-amplified cell lines but not of other genes in these metabolic pathways." (PMID 36388465, 2022). "Proteomic profiling of small number of patients with breast cancer with different subtypes indicated that GLS and TYMS are highest in TNBC, consistent with the immunoblot data from cell lines." (PMID 36388465, 2022). "Increased glutamine metabolic activity has been observed in HER2-positive breast cancer tissue compared with other subtypes of breast cancer, through upregulation of glutamine metabolic proteins including glutaminase 1 (GLS1) and glutamate dehydrogenase (GDH)." (PMID 33367952, 2021). "This study aimed to evaluate the expression and prognostic significance of glutaminase in luminal breast cancer (BC)." (PMID 34439127, 2021). "As we previously noted, glutaminolysis can be inhibited through GLS to overcome glutamine dependency in HR+ breast cancer cells that have developed resistance to several therapeutic agents." (PMID 34638293, 2021). "C-Myc was shown to promote glutamine metabolism in several breast cancer cell lines by upregulating a glutamine transporter as well as the glutamine processing enzyme, glutaminase." (PMID 33266219, 2020). "A panel of eleven breast cancer cell lines was used to investigate the anti-proliferative effects of the glutaminase inhibitors CB-839 and BPTES in different types of culture medium, with or without additional pyruvate supplementation." (PMID 32450839, 2020). "Enhanced plasticity and metabolic redundancy have been previously observed in CB-839-resistant breast cancer 63, 64, although the precise mechanisms of glutaminase inhibition resistance in CRC remain understudied." (PMID 33042274, 2020). "As the product of oncogene JUN, c-Jun directly binds to the GLS promoter which increases gene expression in breast cancer cells." (PMID 32937954, 2020). "In various cancers, including chemotherapy-resistant brain, pancreatic, and breast cancer, 968, an inhibitor of GAC, a shorter isoform of glutaminase, also has potent antitumor effects." (PMID 32397535, 2020). "A prior study has shown that silencing of GLS leads to re-sensitization of taxol-resistant breast cancer, suggesting its key role in taxol-resistance." (PMID 33173435, 2020). "In agreement, GLS has already been reported as a critical enzyme for EMT induction in breast cancer and essential for migration properties in colorectal cancer." (PMID 32850411, 2020). "Another study showed that highly invasive and drug-resistant breast cancer cells presented increased glutamine metabolism, increased glutamate-to-glutamine ratio, and a higher glutaminase expression compared to non-invasive breast cancer cells." (PMID 32211323, 2020). "Meanwhile, elevated SIRT5 expression in breast cancer mediates glutaminase desuccinylation and protects glutaminase from ubiquitin-mediated degradation; this effect has been associated with a poor prognosis in breast cancers." (PMID 33117804, 2020). "The glutamine metabolic pathway is important for cancer growth and GLS has been studied in both human and canine mammary tumours." (PMID 32857815, 2020).
breast carcinoma (continued). "There is an association between GLS1 (an isoform of GLS) expression, malignancy, and tumour type of canine mammary tumours." (PMID 32857815, 2020). "To determine if the GLS2 and GLS inverse expression pattern we observed in the cell lines is also evident in breast cancer patient samples, we compared GLS and GLS2 copy numbers in samples from 1075 patients using data from The Cancer Genome Atlas (TCGA)." (PMID 31652551, 2019). "The glutaminase inhibitor CB-839 (Calithera) is currently being tested in clinical trials for several malignancies including breast cancer (clinicaltrials.gov, ID: NCT02071862)." (PMID 31088535, 2019). "For example, our analysis showed that glutaminase is frequently reported in PubMed abstract in reference to breast cancer, whereas the classic mitochondrial glutamate oxidation enzyme, GLUD1, has only been once reported in this context." (PMID 31231467, 2019). "In this study, we have evaluated the treatment response to the glutaminase inhibitor CB-839 in two breast cancer PDX models." (PMID 31088535, 2019). "Metabolic redundancy or plasticity can rescue cancer cells from glutaminase inhibition, and our understanding of metabolic characteristics within the molecular breast cancer subtypes remains limited." (PMID 31088535, 2019). "In line with results obtained from analysis of cell lines, expression of GLS2 is inversely correlated with GLS in 52% of the cancer types analyzed, including breast cancer." (PMID 31652551, 2019). "The GLS gene had a noticeable clinical significance in the assessment of recurrence, metastasis, and death in patients with breast cancer, in which this gene was upregulated." (PMID 30871151, 2019). "GLS levels were reported to increase in TNBC breast cancer cells but the significance of GLS protein levels in TNBC tumors remain to be elucidated." (PMID 31428575, 2019). "Our study illustrates the shortcomings of currently proposed predictive biomarkers of response to glutaminase inhibition in breast cancer." (PMID 31088535, 2019). "This revealed that alkaline phosphatase treatment remarkably reduced glutaminase activity in lung cancer cells, hepatocarcinoma cells, breast cancer cells, and cervical cancer cells." (PMID 29515166, 2018). "BPTES treatment significantly altered the levels of a number of metabolites in both breast cancer cell lines, and such altered levels clearly indicate the cells' sensitivity to the glutaminase inhibitor BPTES." (PMID 29868609, 2018). "Investigations using human breast cancer cell lines have shown that the oncogene, Myc, enhances the expression of glutaminase and thus increases glutamine metabolism in mitochondria." (PMID 29868609, 2018). "The results of these phenotypic rescue experiments firmly established the on-target specificity of the GLS shRNA and demonstrated that the effects of GLS knockdown reflect dependency on this target in basal breast cancer cell lines." (PMID 28950000, 2017). "Our analysis revealed that, unlike HER2 positive, Luminal A, Luminal B, or normal-like cancer types, many of the basal subtype breast cancer samples consistently displayed simultaneous up- and down- regulation of GLS and GLUL gene expression, respectively." (PMID 28950000, 2017). "To correlate glutamine levels with breast cancer subtype, we first analyzed the expression of GLS and GLUL as reported in The Cancer Genome Atlas (TCGA) database." (PMID 28950000, 2017). "Consistent with our study, analysis of metabolite flux in primary breast cancer tissue revealed that TNBC tumors have a higher glutamate to glutamine ratio denoting increased GLS activity in TNBC cells." (PMID 28950000, 2017). "GAC has been demonstrated to be the predominant isoform of glutaminase in breast cancer cells, and our previous studies showed that the GAC specific inhibitor 968 effectively inhibited the growth of breast cancer cells." (PMID 28039459, 2017).